ROR1 (ROR family WNT receptor 1)
Diseases named in the same sentence as ROR1 in open-access papers (continued):
Sharing a sentence is not in itself a finding about the gene and the disease.
cancer (continued). "Receptor Tyrosine Kinase Like Orphan Receptor 1 (ROR1), is an onco-embryonic antigen that is expressed during embryogenesis, and a variety of human cancers including CLL." (PMID 35406490, 2022). "Fortunately, receptor tyrosine kinase-like orphan receptor 1 (ROR1) is among a few good cancer targets that is aberrantly expressed on various tumors but has a low expression on normal tissue, suggesting it as a good candidate for CAR-T therapy." (PMID 35892876, 2022). "Both CARs target ROR1+ cancer cells specifically, but CAR with a shorter IgG4 hinge exhibits a higher surface expression and better in vitro functionality." (PMID 35892876, 2022). "Preclinical studies are also developing and evaluating additional therapeutic strategies targeting ROR1 in a growing list of cancers." (PMID 36289823, 2022). "Future studies will need to show efficacy of F i-CAR-T cells in a wider repertoire of ROR1 + cancer models." (PMID 35659040, 2022). "Activation of glucocorticoid receptor also regulates the receptor tyrosine kinase ROR1 expression and the Hippo pathway, which are importantly involved in cancer progression." (PMID 35729536, 2022). "Enhanced expression of Ror1 and/or Ror2 in cancer cells can promote their proliferation, migration, invasion, survival or chemoresistance through activation of Rho-family GTPases, c-Src, MAP kinases or Akt in Wnt5a-dependent and/or -independent manners." (PMID 35493090, 2022). "The low or absent expression in normal adult tissues and its high expression in several cancer types have made ROR1 an ideal target candidate for cancer therapy." (PMID 35892876, 2022). "Given the aberrant expression of ROR1 in cancer cells and its important role in cell proliferation, new therapeutic strategies targeting ROR1 have been evaluated in preclinical studies and clinical trials." (PMID 36557069, 2022). "Receptor tyrosine kinase-like orphan receptor 1 (ROR1), a member of ROR family, is a protein encoded by ROR1 gene, and it is overexpressed in cancer." (PMID 36497465, 2022). "Even ROR1+ cancer cells can be captured by observing the red fluorescence intensity with a special fluorescence microscope based on a smart phone." (PMID 36363856, 2022). "The clinical observations that ROR1 and ROR2 are associated with disease progression and metastasis in many cancer patients have inspired researchers to investigate the role of both co-receptors in the underlying cellular processes." (PMID 33445713, 2021). "Several studies have reported the upregulation of ROR1 or ROR2 in chemoresistant cancer cell lines as well as in patient-derived tissues after chemo- or targeted therapy." (PMID 33445713, 2021). "When we co-cultured ROR1-specific CAR T cells with ROR1-expressing K562 human cancer cells, we found that pentanoate-pretreated cells elevated the production of CTL-related cytokines IFN-γ and TNF-α." (PMID 34210970, 2021). "Still, both ROR1 and ROR2 are overexpressed in many cancer entities and studies have linked overactive WNT/ROR signaling to key tumorigenic processes such as cell survival, proliferation, and invasiveness." (PMID 33445713, 2021). "Further research is required to understand the role of ROR1 in these processes in general as well as in the context of cancer." (PMID 33445713, 2021). "This review provides updated information about the structural and functional features of ROR1, its role in cell signaling, and anti-cancer therapies targeting ROR1." (PMID 34123850, 2021). "Taken together, its crosstalk with these two pathways is probably responsible for the pro-survival effects of ROR1 observed in many cancer cells." (PMID 33445713, 2021). "ROR1 has oncofetal expression, as it is an embryonic protein that is not normally expressed in differentiated cells, but can be re-expressed in cancer cells." (PMID 34088900, 2021).
cancer (continued). "Further in vitro studies have indeed confirmed higher expression of typical epithelial factors (e.g., CK19, CDH1) and lower expression of mesenchymal factors (e.g., SNAI2, ZEB1, VIM) after ROR1 or ROR2 knockdown in cancer cells." (PMID 33445713, 2021). "Receptor tyrosine kinase ROR1 plays an essential role in embryogenesis and is overexpressed in many types of malignant tumors." (PMID 34123850, 2021). "ROR1-targeted therapy is expected to be more cancer-specific than chemotherapy, with fewer side effects due to its oncofetal expression." (PMID 34088900, 2021). "Meanwhile it became evident that ROR1 plays a major role in cancer cell survival by promoting proliferation, while at the same time counteracting apoptosis." (PMID 33445713, 2021). "Taken together, the data imply that both ROR1 and ROR2 are associated with highly malignant cancer cell phenotypes characterized by high motility and aggressiveness." (PMID 33445713, 2021). "The overexpression of ROR1 in various types of human cancers has attracted interest from the field of drug discovery." (PMID 34445128, 2021). "In the case of monoclonal antibody against ROR1, at least there is a mAb (called Cirmtuzumab) in clinical trials which is an evidence for introducing ROR1 as a cancer target 42,43." (PMID 32695279, 2020). "The results from this part are in line with other reports emphasizing usefulness of ROR1 targeting by monoclonal antibody as a cancer therapy strategy 24,34,35." (PMID 32695279, 2020). "Receptor tyrosine kinase-like Orphan Receptor 1 (ROR1) is one of the promising cell surface antigens for targeting cancer cells." (PMID 32695279, 2020). "ROR1 signaling that contributes to the maintenance, self-renewal, and drug resistance of CSCs has been uncovered for some cancers." (PMID 31382410, 2019). "This review focuses on the latest advances in our understanding regarding the crosstalk of Wnt5a-ROR1 and Hippo-YAP/TAZ or BMI-1 in tumorigenesis and drug resistance and discusses novel strategies for the therapeutic targeting of ROR1 in cancer treatment." (PMID 31382410, 2019). "Multiple preclinical studies have indicated that combination therapies co-targeting ROR1 and other oncogenic pathways are more effective in killing drug-resistant cancer cells than a single agent alone." (PMID 31382410, 2019). "On the other hand, in certain cancers such as breast, ovary, and lung, ROR1 protein is restricted to cells showing mesenchymal/metastatic features." (PMID 30832318, 2019). "The expression of ROR1 has been associated with EMT and cancer stem cell phenotypes in different cancers previously, but there is no data in the context of HCC." (PMID 30832318, 2019). "ROR-1 expression is found to increase in numerous blood and solid malignancies, but is very low in healthy adult tissues; these properties of ROR-1 make it a potential target for cancer immunotherapy." (PMID 31008116, 2019). "For instance, in a non-carcinoma context, ROR1 was shown to be decreased during acquisition of metastatic features." (PMID 30832318, 2019). "ROR1 is a novel target for cancer immunotherapy as it is overexpressed in a number of malignancies without significant expression in normal adult tissues." (PMID 29850623, 2018). "In this work we have examined the target protein Ror1, whose expression changes during certain types of cancers." (PMID 28432357, 2017). "The target protein (Ror1) was selected on the basis of previous reports concluding that Ror1 can act as a novel target for designing an efficient drug for cancer treatment." (PMID 28432357, 2017). "Despite these findings, targeting of ROR1 has been suggested as a novel strategy for cancer therapy." (PMID 29212222, 2017). "Dysregulation of RTKs, including ROR1, has been demonstrated in various cancers and targeting of RTKs has served as a strategy for cancer treatment." (PMID 29212222, 2017).
cancer (continued). "Head-to-head comparison in a panel of ROR1 positive cancer cell lines demonstrated that the ROR1 BiTE containing an scFv directed against the Fr domain yielded consistently superior and reproducible cytotoxicity compared with BiTEs targeting the Ig domain." (PMID 28811962, 2017). "We have developed a humanized bi-specific T-cell engager (BiTE) targeting receptor tyrosine kinase-like orphan receptor 1 (ROR1), a cell surface antigen present on a range of malignancies and cancer-initiating cells." (PMID 28811962, 2017). "A possible mechanism was suggested that ROR1 played a critical role in epithelial- mesenchymal transition (EMT) for cancer metastasis." (PMID 27830754, 2016). "The specific expression of ROR1 in cancer cells makes it a potential target for small-molecule TKIs and monoclonal antibodies (mAbs) for cancer treatment." (PMID 27830754, 2016). "The receptor tyrosine kinase-like orphan receptors (ROR) family contains the atypical member ROR1, which plays an oncogenic role in several malignant tumors." (PMID 26576539, 2015). "To date, very little is known about the functions of ROR1 and its role in human cancers and should be further investigated." (PMID 25978653, 2015). "The discovery of ROR1 expression in CLL and other cancers has informed a diverse array of research on immuno-based strategies to target ROR1." (PMID 24752542, 2014). "A growing literature has established ROR1 as a marker for cancer, such as in CLL and other blood malignancies." (PMID 24752542, 2014). "ErbB2 or HER2/neu, as well as ROR1 are members of the type I RTKs contributing to the malignant phenotype of several human cancers." (PMID 24205204, 2013). "When silenced for ROR1, cancer cells were more sensitive to spontaneous apoptosis and had an impaired cell growth." (PMID 22403610, 2012). "The findings suggest that the interaction between acidocin A and ROR-1 may disrupt crucial signaling pathways involved in cancer cell survival, positioning it as a viable candidate for further preclinical and clinical development as an anticancer agent." (PMID 41477115, 2025). "ROR1 is a receptor shown to be significant in embryonic development and cancer." (PMID 38310345, 2025). "ROR1, a tumor-associated antigen (TAA), is widely expressed in various cancers." (PMID 40723210, 2025). "Importantly, inhibiting ROR1 using an anti-ROR1 monoclonal antibody or shRNA increased the efficacy of anti-cancer drugs, suggesting that ROR1 inhibition can assist in overcoming chemoresistance." (PMID 40869147, 2025). "ROR1 expression in CSCs contributes to multiple cancer malignancies." (PMID 40869147, 2025). "The general role of ROR1 in cancer has been extensively reviewed elsewhere." (PMID 40869147, 2025). "However, in the context of malignancy, aberrant ROR1 expression has been widely documented across various cancers, supporting its role in tumorigenesis and drug resistance." (PMID 41479906, 2025). "However, ROR1 reappears in a variety of cancers, particularly those characterized by a less differentiated state, suggesting a link to the stemness properties of cancer cells." (PMID 40869147, 2025). "Finally, we provide an up-to-date summary of the promising therapeutic strategies targeting ROR1 that overcome conventional cancer treatment limitations." (PMID 40869147, 2025). "Moreover, a meta-analysis of multiple patients with cancer identified that high ROR1 expression correlated with poor prognosis." (PMID 40723210, 2025). "Many functional findings show that ROR1 is linked to non-canonical WNT-signaling to promote cancer cell survival, growth, and invasion, and ROR1 exerts cellular signaling in both kinase-dependent and independent mechanisms." (PMID 38296962, 2024). "The Wnt receptor ROR1 has emerged as a promising therapeutic target in various cancers." (PMID 39767561, 2024).
cancer (continued). "The receptor tyrosine kinase-like orphan receptor 1 (ROR1) has been identified as a potential biomarker in human cancers and represents a promising target for an immunotherapy approach, which could be considered for future treatment strategies." (PMID 38846943, 2024). "Additionally, our findings suggest that the small molecule ROR1 inhibitor, PGG, selectively targets ROR1-expressing cancer cells and suppresses proliferation, anti-apoptosis, migration, invasion, and cell cycle progression." (PMID 39000112, 2024). "ROR1 inhibition for the treatment of cancer is emerging as a potential therapeutic strategy." (PMID 39000112, 2024). "It is important to note that while we characterize the anti-cancer properties of PGG through its ability to modulate ROR1-mediated AKT-GSK3β signaling based on prior literature and our results, it is possible that PGG can also exhibit these effects by impacting other cancer-associated markers." (PMID 39000112, 2024). "ROR1 can be a powerful target due to its specific upregulation in cancer." (PMID 39000112, 2024). "It has been reported that ROR1 signaling may regulate the maintenance, self-renewal, and drug resistance in breast and other cancers." (PMID 38296962, 2024). "By targeting ROR1, these therapies can disrupt specific oncogenic signaling pathways that cancer cells depend on for survival, proliferation, and metastasis, potentially offering durable remissions and improved outcomes for patients with aggressive malignancies." (PMID 39551787, 2024). "Numerous studies have shown that inhibiting ROR1 can effectively target cancer." (PMID 39000112, 2024). "Moreover, targeting ROR1 using different drug formulations represents a promising strategy for overcoming drug resistance in cancer treatment." (PMID 39551787, 2024). "At the same time, since ROR1 is expressed on the surface of cancer cells, monoclonal antibodies against ROR1, that induce cytotoxicity, could represent a therapeutical approach." (PMID 39551787, 2024). "Indeed, based on the relevance of ROR1 expression in human cancers, cirmtuzumab was developed as a humanized antibody inhibiting Wnt-5a-ROR-induced signaling, which then entered a phase I clinical trial for CLL patients." (PMID 37237541, 2023). "In particular, we demonstrated that glucocorticoid-mediated ROR1 upregulation in OC could promote cancer stem-cell phenotype and drug resistance." (PMID 37400436, 2023). "Though we identify that strictinin induces anti-cancer effects via the modulation of ROR1-mediated AKT-GSK3β signaling, it is important to note that strictinin may have other modes of action that warrant further investigation." (PMID 38213538, 2023). "Importantly, ROR1/STAT3 expression was also detected in cancer-associated fibroblasts or CAFs, which are often associated with worse disease prognosis in many cancers." (PMID 37400436, 2023). "ROR1 is an oncofetal RTK-like protein that has an emerging role in cancer." (PMID 38213538, 2023). "Importantly, the CCA-specificity of ICAM1 is higher than many common cancer targets such as ROR1, HER2, EGFR, VEGFR, and P-selectin." (PMID 37717087, 2023). "Moreover, blockade of ROR1 with an anti-ROR1 mAb (cirmtuzumab) reduced the downstream signaling pathway and decreased the invasiveness of cancer cells and their ability to persist after chemotherapy." (PMID 36873868, 2023). "However, ROR1 is expressed by neoplastic cells of many cancer types making it a potential target for cancer therapy." (PMID 37029329, 2023). "Strictinin had minimal impact on RWPE-1 cells (normal prostatic epithelium) and moderate phenotypic anti-cancerous effects on DU145 cells (ARneg-AI cancer), which is most likely due to the minimal and moderate expression of ROR1 found in RWPE-1 cells and DU145 cells, respectively." (PMID 38213538, 2023). "A pathologic expression of ROR1 is seen in some hematologic and solid tumor cancers." (PMID 38068428, 2023).
cancer (continued). "ATL II inhibits cancer cell proliferation and causes apoptosis primarily through regulating the PI3K/Akt, JAK2/STAT3, Ras/ERK, JNK/ERK-Nrf2-ARE, and LncRNA XIST/miR-30a-5p/ROR1 signaling pathways to treat colon, gastric, lung, melanoma, breast, and prostate cancers." (PMID 37241729, 2023). "In this cancer, retinoic acid, used as a therapeutic agent for over a decade, was shown to bind to the promoters of ROR1 and WNTA5 to regulate their transcription, reducing cell proliferation and promoting cell differentiation, as evidenced by the increased expression of synaptophysin." (PMID 36873868, 2023). "Treatment with the anti-ROR1 mAb D10, could modulate and inhibit the migration of these cancer cells in vitro and in vivo." (PMID 36873868, 2023). "Studies have shown that inhibiting ROR1 effectively targets many forms of ROR1-expressing cancers." (PMID 38213538, 2023). "Interestingly, the expression of ROR1 in OC stromal cells was previously observed in a pan-cancer IHC analysis of OC subtypes." (PMID 37400436, 2023). "Furthermore, Ror1-mCherry and YFP-Rif accumulated on the front surface with filopodia, suggesting that Ror1 and Rif are involved in the formation and/or function of filopodia during cancer cell migration through 3D matrices." (PMID 37703992, 2023). "siRNA against either Ror1 or Rif drastically inhibited the invasive migration of the cancer cells." (PMID 37703992, 2023). "Based on our previous research that identified ROR1 expression to be most upregulated in the PC3 (ARneg-AI cancer) cell line, we further investigated whether strictinin suppressed ROR1 and downstream cancerous signaling in PC3 cells." (PMID 38213538, 2023). "ROR1 is of importance in oncogenesis and is overexpressed in several cancers, such as NSCLC." (PMID 37111634, 2023). "ROR1 activity induces cancer cell survival and inhibits apoptosis." (PMID 37779899, 2023). "Blocking ROR1 phosphorylation with mAbs drove cancer cells into apoptosis." (PMID 36873868, 2023). "High ROR1 associated with a worse EFS in HR + HER2- patients with high post-treatment residual cancer burden (RCB-II/III) (HR 1.41, 95% CI = 1.11–1.80) but not in patients with minimal post-treatment disease (RCB-0/I) (HR 1.85, 95% CI = 0.74–4.61)." (PMID 37029329, 2023). "Change in ROR1 expression in cancer cells could also contribute to αROR1-CAR T cell cytotoxicity, however, our in vitro assay data showed that ROR1 expression was not repressed by TIFP in A549 cells." (PMID 35484298, 2022). "Since the ROR1/2 pathway is potentially both druggable and therapeutically efficacious, it is imperative to gain a clear understanding of the role this pathway plays in various cancers." (PMID 36289823, 2022). "It was suggested that ROR1 is a common autoantigen in cancer patients." (PMID 36497309, 2022). "This study aimed to identify the prognostic value of ROR1 expression in cancers." (PMID 36557069, 2022). "In the present study, we found high expression of ROR1 in WT cancer tissues." (PMID 35480093, 2022). "Furthermore, up-regulated expression of Ror1 can be mediated by STAT3 in various types of cancer cells, thereby promoting proliferation of cancer cells in Wnt5a-dependent or -independent manners." (PMID 35493090, 2022). "The present meta-analysis assessed whether ROR1 expression has an impact on survival in various types of cancer using published data." (PMID 36557069, 2022). "Besides, a higher expression of MCSP and ROR1, cancer markers, with strong median fluorescence intensities (MFI) were found." (PMID 35080744, 2022). "All human cancer cell lines that were tested expressed ROR1 antigen at different levels and thus could be a target of ROR1 CAR-T in the study." (PMID 35892876, 2022). "Proteins used as cancer markers, such as ROR1, EpCAM, or CA72-4, were observed on the uEVs." (PMID 35740652, 2022).